APC (APC regulator of Wnt signaling pathway)
Diseases named in the same sentence as APC in open-access papers (continued):
Sharing a sentence is not in itself a finding about the gene and the disease.
diffuse large B-cell lymphoma (12 papers, 2019 to 2022). "Research has found that the long noncoding RNA Smad5-AS1 can act as a competitive RNA for miR-135B-5p to upregulate APC expression and inhibit the proliferation of diffuse large B cell lymphoma cells." (PMID 36224652, 2022). "Similarly, SMAD5-AS1 is reported to be a ceRNA of miR-135b-5p to upregulate APC expression in diffuse large B cell lymphoma." (PMID 31921616, 2019). "The expression of circ-APC (hsa_circ_0127621) is decreased in diffuse large B-cell lymphoma (DLBCL) tissues, cell lines, and plasma by microarray assays." (PMID 35116058, 2021). "Circ-APC (circ_0127621) was downregulated in diffuse large B-cell lymphoma (DLBCL) and its levels in plasma can distinguish patients from healthy controls." (PMID 33195421, 2020). "In diffuse large B-cell lymphoma (DLBCL), circAPC (hsa_circ_0127621), derived from the APC exon 7 to exon 14, decreases cell proliferation." (PMID 33710806, 2021). "Augmented expression of circ-APC inhibited the growth of diffuse large B-cell lymphoma (DLBCL) cells in vitro and in vivo by recruiting TET1 to the promoter of APC, subsequently resulted in the activation of canonical Wnt/β-catenin signaling pathway." (PMID 33069241, 2020). "In diffuse large B-cell lymphoma (DLBCL), the evidence shows that cell proliferation is impeded by direct binding of lncRNA SMAD5-AS1 to miR-135b-5p, resulting in the increased expression of APC and the decreased activation of the Wnt/Beta-catenin pathway." (PMID 35432537, 2022).
esophageal squamous cell carcinoma (12 papers, 2021 to 2025). Esophageal squamous cell carcinoma (ESCC) is a type of esophageal carcinoma (EC) that can affect any part of the esophagus, but is usually located in the upper or middle third. "In contrast, APC is rarely mutated in other types of cancer, such as oesophageal squamous cell carcinoma (ESCC), which has only ~1.5% APC mutation." (PMID 34155197, 2021). "Previously, we demonstrated that APC/C coordinated the tricarboxylic acid (TCA) cycle at late G1 phase in esophageal squamous cell carcinoma (ESCC)." (PMID 38783346, 2024). "METTL3 can promote the cell proliferation of esophageal squamous cell carcinoma (ESCC) by decreasing APC expression mediated by APC mRNA m6A‐dependent YTHDFs binding." (PMID 36260366, 2023). "METTL3 upregulates the m6A modification of adenomatous polyposis coli (APC) RNA in esophageal squamous cell carcinoma (ESCC) cells, which recruits YTHDF for APC mRNA degradation." (PMID 37192910, 2023). "Elevated METTL3 strengthened the m6A levels of APC mRNA in esophageal squamous cell carcinoma and subsequently recruited YTHDF to degrade APC mRNA, ultimately activating cancer cell proliferation and aerobic glycolysis." (PMID 37344779, 2023). "Decreased APC increases β-catenin, cyclin D1, c-Myc, and PKM2 expression, resulting in mouse aerobic glycolysis, cell proliferation, and enhanced esophageal squamous cell carcinoma (ESCC) formation." (PMID 35087575, 2021). "In esophageal squamous cell carcinoma (ESCC), METTL3 and YTHDF collaborate to downregulate adenomatous polyposis coli (APC) expression, thereby activating the Wnt/β‐catenin signaling pathway and promoting aerobic glycolysis." (PMID 38721006, 2024).
glioblastoma (12 papers, 2016 to 2025). The most malignant astrocytic tumor (WHO grade IV). "Close connections between large deletions and mutations in the APC gene and increased β-catenin expression in glioblastoma were also established." (PMID 34064046, 2021). "It is also evident that large deletions and mutations in the APC gene increase the level of β-catenin expression in glioblastomas." (PMID 34064046, 2021). "Genetic changes of APC exon 11 were analyzed in 27 glioblastoma samples that were available for the analysis, nine (33%) of which were homozygous i.e., uninformative." (PMID 34064046, 2021). "Eight glioblastoma samples with genetic change in APC exon 11 showed moderate expression of total β-catenin in 62.5% and unphosphorylated β-catenin in 50% of samples." (PMID 34064046, 2021). "We hypothesized that YTHDF2 in glioblastoma could bind to m6A sites on APC and GSK-3β mRNAs, promoting their degradation and activating the Wnt-β-catenin pathway." (PMID 38637831, 2024). "Some known oncogenes and tumour suppressors are only captured by RUBIC, such as MDM4 in breast, APC in colon and EGFR in Glioblastoma." (PMID 27396759, 2016). "RIP-qPCR experiments demonstrated that YTHDF2 binds to APC and GSK-3β mRNAs in glioblastoma cells." (PMID 38637831, 2024). "In glioblastoma (GBM) cell lines, a combination treatment of TAME and apcin effectively decrease cell viability and induces mitotic arrest, indicating that drugs for targeting APC/C are promising chemotherapeutics." (PMID 37176148, 2023).
rectal adenocarcinoma (12 papers, 2015 to 2026). "In an analysis of TCGA colon and rectum adenocarcinoma samples (n=196), the APC variant T1396Nfs*3 was detected in 3 cases." (PMID 39435285, 2024). "Consistent with previous findings highlighting the frequent occurrence of APC mutations, we observed a high prevalence of FSCs within the APC gene in colon and rectal adenocarcinomas." (PMID 40443655, 2025). "For rectal adenocarcinoma, we observed that APC DNA methylation was negatively correlated with gene expression on multiple probes in the non-promoter region, but the opposite result was obtained in the skin cutaneous melanoma case." (PMID 35303016, 2022). "In APC mutation groups of COAD and rectum adenocarcinoma (READ), most SIGLEC family genes were significantly down-regulated; in the CTNNB1 mutation group of LIHC, all SIGLEC family genes were down-regulated (10 out of 14 achieved significance)." (PMID 33240817, 2020). "Intriguingly, in TCGA data on rectal adenocarcinoma, we found that two males among 137 patients harbored WAS mutations (R309H and D292N), who also carried APC mutations (R1114X; S1400L/S2761L)." (PMID 30619485, 2018). "A JRT with rectal adenocarcinoma did not harbor the germline APC variant and was determined to be a sporadic case." (PMID 35717217, 2022). "Finally, a key feature of the primary rectal adenocarcinoma was APC and CDH13 methylation, suggesting an aberrant activation of the wingless signaling pathway that is considered a nearly ubiquitous event in CRC." (PMID 26231173, 2015).
esophageal adenocarcinoma (11 papers, 2005 to 2025). A malignant tumor with glandular differentiation arising predominantly from Barrett mucosa in the lower third of the esophagus. "An altered Wnt-signaling activation has been reported during Barrett’s esophagus progression, but with rarely detected mutations in APC and β-catenin (CTNNB1) genes." (PMID 30841855, 2019). "However, loss of heterozygosity of the SMAD4 and APC loci shows a heterogeneous pattern, indicating intratumor heterogeneity of esophageal adenocarcinoma." (PMID 28376920, 2017). "The hypermethylation of the APC gene promoter region and its consequent inactivation have been studied in various neoplasms, including Barrett’s esophagus." (PMID 40149421, 2025). "For oesophageal squamous cell carcinoma and oesophageal adenocarcinoma, methylation of certain genes such as APC and DAPK have been highlighted as promising biomarkers for prognostication, but these studies are limited and more comprehensive research is needed." (PMID 30087854, 2018). "Similar stage-dependent increase in methylated APC DNA was also noted in patients with oesophageal adenocarcinoma, which may be related to the heavy tumour load in patients with more advanced cancer." (PMID 15942635, 2005). "Adenomatous Polyposis Coli (APC) promoter methylation is a characteristic of gastrointestinal cancers, and hypermethylation of the CDKN2A/p16 promoter leads to its inactivation in esophageal adenocarcinoma." (PMID 41150792, 2025).
gastric polyposis (11 papers, 2018 to 2026). "The daughter was brought to the veterinary hospital at 8 years of age with a gastric polyp, and genetic testing revealed that she had inherited the APC variant." (PMID 37505844, 2023). "Targeted genomic sequencing revealed that most gastric polyps did not arise via APC loss of heterozygosity." (PMID 37943618, 2023). "In our study, we found multiple gastric polyps in six of eight carriers, including the proband who had undergone EGD, which is in line with previous studies showing that the gastroduodenal adenoma is related to the variants of APC in codons 564–1493." (PMID 33740971, 2021). "On the other hand, by testing the BMPR1A variant carrier for germline mutations in promoter 1B of APC gene, we could exclude GAPPS, thus reinforcing the causal link between BMPR1A and gastric polyposis." (PMID 31514334, 2019).
juvenile polyposis syndrome (11 papers, 2019 to 2023). Juvenile gastrointestinal polyposis (JIP) is a rare condition characterized by the presence of juvenile hamartomatous polyps in the gastrointestinal (GI) tract.
leukemia (11 papers, 2014 to 2025). A malignant (clonal) hematologic disorder, involving hematopoietic stem cells and characterized by the presence of primitive or atypical myeloid or lymphoid cells in the bone marrow and the blood. "BI-D1870, the inhibitor of RSK, potentiated anti-leukemia activity of vincristine, which prevent the association of activator CDC20 with APC/C and impeded mitosis exit." (PMID 34051812, 2021). "APC and MDM2 in the MDM2:APC cross-talk are both tumor suppressors; they co-regulate DNA polymerase- β which is reported to be hyper-activated in a cis-diamminedichloroplatinum(II) resistant P388 murine leukemia cell line." (PMID 25599599, 2015). "Therefore, to specifically target APC, enhance the phenotype, and gain access to larger number of cells, we investigated the effect of APC silencing in CEM leukemia T cells, a suitable model for T cell migration analyses." (PMID 35417240, 2022).
osteoma (11 papers, 2013 to 2025). A benign, well-circumscribed, bone-forming neoplasm predominantly composed of lamellar bone. "According to the clinical data available, none of the patients (including those with a CTNNB1 wild type osteoma), had multiple osteomas or stigmata implying a syndromal association and thus potential involvement of the APC gene." (PMID 34725446, 2022). "Furthermore, constitutional APC mutations leading to accumulation of beta-catenin is associated with the development of osteoma, a benign bone lesion that shares some morphological features with osteoid osteoma and osteoblastoma." (PMID 24236197, 2013). "The literature to date contains no large studies of the prevalence of APC germline mutations in patients with osteomas." (PMID 35158896, 2022). "However, there are reports of a child with osteoma and no colorectal phenotype at the time of diagnosis who was found to have a de novo frameshift APC mutation, and of a 16-year-old patient with Gardner fibroma as well as osteoma with a germline APC mutation." (PMID 35158896, 2022).
sarcoma (11 papers, 2012 to 2025). A usually aggressive malignant neoplasm of the soft tissue or bone. "All three P/LPGVs identified in APC were concordant, with one each in sarcoma and ovarian and brain cancers." (PMID 41465149, 2025). "We also demonstrated that tankyrase inhibitors induce Axin1/2 stabilization in human MDA-MB-231 basal-like cells, human MCF-7 epithelial-like cells and mouse EMT6 sarcoma-like cells, all of which are breast cell lines of diverse origins but with normal APC." (PMID 23144924, 2012).
Sepsis (11 papers, 2006 to 2025). Sepsis is defined as life-threatening organ dysfunction caused by a dysregulated host response to infection. "Although early use of rhAPC failed in sepsis because of bleeding risk, growing mechanistic insight into the cytoprotective actions of APC and the development of safer APC analogues have renewed interest in its potential value in selected subgroups." (PMID 41567206, 2025). "This species difference has clinical consequences with activated protein C (APC) being approved for the treatment of sepsis based on animal studies and yet had to be withdrawn from the market due to a lack of efficacy." (PMID 37350961, 2023). "In recognition of these properties, recombinant human aPC (rhAPC) was developed as a therapeutic agent for uncontrolled sepsis, with promising initial results in a large multi-center randomized trial." (PMID 27008408, 2016). "Recombinant activated protein C (aPC) had been approved for the treatment of patients with severe sepsis in 2001, after the PROWESS Study showed that it was able to significantly reduce mortality." (PMID 24070065, 2013). "In addition, rTM has been approved in Japan for sepsis-associated DIC, and it improves endothelial function by promoting APC generation, reducing thrombin activity, and alleviating endothelial inflammation." (PMID 41567206, 2025). "However, down-regulation of TCR and APC pathway and up-regulation of complement-coagulation cascade pathway was found in most of adult and pediatric sepsis patients." (PMID 33667236, 2021). "The role of recombinant activated protein C (aPC) during sepsis is still controversial." (PMID 24070065, 2013). "This is nicely illustrated by the implementation processes of several strategies in the ICU in the last decade, such as the use of recombinant human-activated protein C (rh-APC) in severe sepsis, and the use of lung-protective mechanical ventilation in patients with acute lung injury." (PMID 17147466, 2006). "That may also explain the up-regulate of APC co-inhibition in the sepsis group of our study." (PMID 37608823, 2023). "APC is an endogen protein with anti-inflammatory, anticoagulant and profibrinolitic properties; it showed to inhibit the generation of thrombin by inactivating factor Va and factor VIIIa and this was thought to be the most important mechanism for its therapeutic action in sepsis." (PMID 24070065, 2013). "However, this is unlikely to be clinically relevant and activated protein C (aPC) is a thrombin inhibitor and was introduced for the treatment of sepsis, however, it was ultimately removed from the market due to the lack of benefit." (PMID 37350961, 2023).
attenuated familial adenomatous polyposis (10 papers, 2005 to 2025). "Three variants are known to exist, FAP and attenuated FAP (previously referred to as Hereditary Flat Adenoma Syndrome) are caused by APC gene defects." (PMID 26436104, 2015). "The clinical impression was attenuated familial adenomatous polyposis (AFAP), with a germline heterozygous truncating APC mutation at codon 215 (CAG to TAG; Gln to stop)." (PMID 15941485, 2005).
inflammatory bowel disease (10 papers, 2014 to 2025). A spectrum of small and large bowel inflammatory diseases of unknown etiology. "DLG5 function is lost in the KAD rat; this protein is also defective in inflammatory bowel disease (IBD), suggesting an association between APC and IBD." (PMID 25288683, 2014).
ovarian tumors (10 papers, 1996 to 2025). "We also somatically tested the complete APC gene for pathogenic variants in these lesions, as finding of pathogenic APC variants in ovarian neoplasms would point at a colonic origin of the lesions." (PMID 29124495, 2018). "CGIs associated with three putative tumor suppressor genes APC, HIC1 and RASSF1 have previously been shown to be frequently hyper-methylated in breast and ovarian tumors when compared to healthy tissue." (PMID 20544021, 2010). "Forty-nine ovarian tumours were examined for loss of heterozygosity (LOH) on chromosome 5 using eight microsatellite markers spanning both arms, including one at the APC locus." (PMID 8679443, 1996). "We also observed that VOPP1 up regulated APC while down regulated β-catenin in ovarian tumor cells." (PMID 40949794, 2025). "Even though APC and SCGB3A1 promoter methylation is less frequent, it is nevertheless associated with early stage ovarian tumours and might also have a diagnostic potential." (PMID 17623056, 2007). "It is not known whether APC is mutated in ovarian tumours or not." (PMID 14520463, 2003). "Consistent with our results, ovarian tumors formed in APC-PTEN knockout model were also negative for inhibin-α staining." (PMID 21695255, 2011). "Genetic changes in the APC gene in ovarian tumours have not been described." (PMID 14520463, 2003).
gastric tumor (9 papers, 2003 to 2025). "miR-106a-3p suppresses APC expression in gastric tumor, while LINC01133 sponges miR-106a-3p to increase APC expression." (PMID 38334836, 2024). "The antisera that react with the specific epitope of the APC protein were used for immuno-histochemical staining to demonstrate the protein expression in gastric tumors." (PMID 28576136, 2017). "Y622* mutated and negative APC protein expressing gastric tumor samples had a high concordance with aneuploid cells." (PMID 28576136, 2017). "Interestingly, TNF-α is known to induce β-catenin nuclear accumulation without APC mutations in gastric tumors." (PMID 27388564, 2016).
Li-Fraumeni syndrome (9 papers, 2007 to 2023).